OTC (ornithine transcarbamylase)
Diseases named in the same sentence as OTC in open-access papers (continued):
Sharing a sentence is not in itself a finding about the gene and the disease.
ornithine transcarbamylase deficiency (17 papers, 2014 to 2025). "Additional evidence for the therapeutic efficacy of ExSpeU1 is provided by its application in correcting splicing mutations in OTC gene detected in patients with ornithine transcarbamylase deficiency (OTCD; MIM 311250)." (PMID 41244709, 2025). "Ornithine transcarbamylase deficiency (OTCD) is a rare hereditary disorder resulting from mutations in the Ornithine transcarbamylase (OTC) gene, which exhibits an X-linked recessive or incomplete dominant inheritance pattern." (PMID 39328593, 2024). "Last, patient O (diagnosed with Ornithine Transcarbamylase deficiency, OTC), showed an unexpectedly higher value for arginine rather than ornithine." (PMID 37101200, 2023). "We aim to analyze the clinical symptoms, blood metabolic profiling and the gene mutation of ornithine transcarbamylase (OTC) in three ornithine transcarbamylase deficiency (OTCD) patients." (PMID 33072985, 2019). "Ornithine transcarbamylase deficiency (OTCD: OMIM#311250) is triggered by mutation in this OTC gene." (PMID 28324312, 2014). "A recent analysis of the XCI pattern in 25 samples of the explanted liver from a 14-year-old female patient with late-onset OTC deficiency showed remarkable intra-organ variation ranging from 46:54 to 82:18 in favor of the active X chromosome with the mutated allele of the OTC gene." (PMID 33925963, 2021). "Mutations in the OTC gene cause OTC deficiency (OTCD; OMIM 311250), an X-linked recessive disorder." (PMID 30175132, 2018). "This study aims to explore the pathogenicity of two missense variants in the OTC gene and investigate the application of preimplantation genetic testing for monogenic (PGT-M) for a family troubled by Ornithine carbamoyltransferase deficiency (OTCD)." (PMID 39039447, 2024). "Ornithine transcarbamylase deficiency (OTCD; MIM 311250) is an X-linked inborn error of the urea cycle caused by mutations in the gene OTC located on chromosome Xp11.4." (PMID 39256843, 2024). "This was also the case in the family with ornithine transcarbamylase deficiency (OTC), where the XCI status in blood cells was random in female carriers, while it was skewed in the liver and correlated with the OTC activity." (PMID 33925963, 2021). "Patient IV‐1 was affected by the X‐link ornithine transcarbamylase deficiency (OTCD, MIM #311250) since he carried a known pathogenic variant, OTC: c.595A > G inherited from his asymptomatic heterozygous mother (IV.3)." (PMID 33611823, 2021). "This study aimed to describe the clinical and biochemical features of Chinese patients with ornithine transcarbamylase deficiency (OTCD), and to investigate the mutation spectrum of OTC gene and their potential correlation with phenotype." (PMID 33272297, 2020). "Ornithine Transcarbamylase Deficiency (OTCD) (OMIM# 311250), the most common of urea cycle defects (UCDs) with an estimated incidence of 1 in 66.000–70.000, is caused by mutations in OTC gene mapping on Xp11.4." (PMID 38167094, 2024).
citrullinemia (15 papers, 2010 to 2026). Citrullinemia is an autosomal recessively inherited disorder of urea cycle metabolism and ammonia detoxification characterized by elevated concentrations of serum citrulline and ammonia. "Plasma metabolites instead highlighted argininemia, citrullinemia, and ornithine transcarbamylase deficiency (q = 0.0644), though the urea cycle and associated pathways metabolite set was not significant (q = 0.197)." (PMID 41431864, 2026). "Human blood citrulline concentrations are potential biomarkers for various diseases, including sepsis, OTC deficiency, and citrullinemia, which are caused by deficiencies in OAT, OTC, and argininosuccinate synthase (ASS), respectively." (PMID 38044351, 2023). "Classical phenylketonuria was the most common aminoacid disorder detected (12%), followed by urea cycle defects (8%) with missense mutations found in half of the phenylketonuria cases and all citrullinemia and ornithine transcarbamylase deficiency patients." (PMID 36468010, 2022). "The three most observed pathologies were citrullinemia type 1, ornithine transcarbamylase (OTC) deficiency and argininosuccinic aciduria." (PMID 36675662, 2022). "Ornithine transcarbamylase deficiency was the most frequent condition (64.4%) (61.2% female) followed by type 1 citrullinemia (21.1%) and argininosuccinic aciduria (9.6%)." (PMID 25433810, 2014). "The six patients (P1, P2, P3, P4, P5 and P6) were clinically and/or biochemically diagnosed with galactosemia, mucopolysaccharidosis type I (MPS I), maple syrup urine disease (MSUD), hyperphenylalaninemia (HPA), citrullinemia and ornithine transcarbamylase (OTC) deficiency, respectively." (PMID 36361642, 2022). "The two main causes are ornithine transcarbamylase deficiency followed by type II citrullinemia." (PMID 33409766, 2021). "CTD performed competitively with pathway-based models of four major urea cycle disorders: argininosuccinic aciduria (MIM:207900), argininemia (MIM:207800), ornithine transcarbamylase (OTC) deficiency (MIM:311250), and citrullinemia (MIM:215700)." (PMID 35449147, 2022). "The six UCDs include deficiency of: 1) carbamyl phosphate synthetase; 2) n-acetylglutamate synthetase; 3) ornithine transcarbamylase; 4) argininosuccinic acid synthetase (also called citrullinemia); 5) argininosuccinase acid lyase and; 6) arginase." (PMID 24775716, 2014). "The 2013 European survey on UCDs management showed that the supplementation of BCAAs occurred only in 3% of patients with a highly variable dose up to 4 g/day protein equivalent, and the two most common conditions were ornithine transcarbamylase (OTC) deficiency and citrullinemia." (PMID 40428324, 2025). "SLEs may be observed in carbamoyl phosphate synthetase I (CPS1) deficiency, ornithine transcarbamylase (OTC) deficiency and citrullinemia." (PMID 36295831, 2022).
hepatocellular carcinoma (9 papers, 2014 to 2024). A malignant tumor that arises from hepatocytes. "OTC downregulation was reported in hepatocellular carcinoma, which shares HIF signaling activation with PGL." (PMID 36841802, 2023). "The downregulated OTC expression level results in accumulated ammonia and has been associated with larger tumor size, advanced grade, and poor prognosis for patients with hepatocellular carcinoma (HCC)." (PMID 37601653, 2023). "Intrigued by these observations, we expressed human (h) and mouse (m) OTC hybrid minigenes in human (HepG2) and mouse (Hepa1-6) hepatoma cell lines, being OTC physiologically expressed in hepatocytes." (PMID 34906067, 2021). "Activities of glucose-6-phosphatase, fructose 1,6-diphosphatase, ornithine transcarbamylase, arginase and xanthine oxidase were measured in thioacetamide induced primary hepatoma and its tumour cell suspension." (PMID 4323228). "However in a range of adult solid cancer cell lines (keratinoctic carcinoma, lung adenocarcinoma, hepatocellular carcinoma and breast carcinoma) OTC was undetectable consistent with our findings here." (PMID 28969007, 2017).
methylmalonic acidemia (6 papers, 2010 to 2025). A genetically heterogenous inherited disorder characterized by abnormalities in the metabolism of lipids and proteins. "Researchers are exploring the potential of mRNA vaccines to treat a variety of rare genetic disorders, such as hereditary tyrosinemia type 1, phenylketonuria, methylmalonic acidemia, propionic acidemia, glycogen storage disease type 1a, and ornithine transcarbamylase deficiency." (PMID 39203999, 2024).
Wilson disease (6 papers, 2014 to 2025). A very rare inherited multisystemic disease presenting non-specific neurological, hepatic, psychiatric or osseo-muscular manifestations due to excessive copper deposition in the body. "In this group of patients, one individual died from ornithine transcarbamylase deficiency and four died from Wilson disease, resulting in a mortality rate of 0.8%." (PMID 38510075, 2024). "There is a wide spectrum of genetic liver diseases worldwide, such as ornithine transcarbamylase deficiency and Wilson's disease." (PMID 33456582, 2021). "Several metabolic diseases, such as Wilson’s disease, NICCD, ornithine transcarbamylase deficiency, and carnitine deficiency, manifest steatohepatitis and cirrhosis." (PMID 34684069, 2021).
Duchenne muscular dystrophy (5 papers, 2016 to 2025). Duchenne muscular dystrophy (DMD) is a neuromuscular disease characterized by rapidly progressive muscle weakness and wasting due to degeneration of skeletal, smooth and cardiac muscle. "When XK gene segment deletions are excessive, they may involve contiguous XK genes, such as the CYBB and RPGR genes, which could result in “Xp21 DNA microdeletion syndrome”, including XLRP, chronic granulomatous disease, Duchenne muscular dystrophy, and ornithine transcarbamylase deficiency (OTC)." (PMID 38343445, 2023). "The gene of OTC was mapped closely to Duchenne muscular dystrophy, which may play a role in myogenesis." (PMID 26911206, 2016).
homocystinuria (5 papers, 2010 to 2023). An autosomal recessive inherited metabolic disorder caused by mutations in the CBS, MTHFR, MTR, and MTRR genes. "Finally, diagnosis of methylmalonic aciduria and homocystinuria, glycogen storage disease, ornithine transcarbamylase deficiency, glutaric acidemia II, mitochondrial complex 1 deficiency, carnitine deficiency, and Schaaf-Yang syndrome was made in 12 out of the 31 patients." (PMID 29581464, 2018). "Elevated levels of L-α aminobutyric acid in the plasma of children have been associated with Reye’s syndrome, tyrosinemia, homocystinuria, nonketotic hyperglycinemia, and ornithine transcarbamylase deficiency." (PMID 36705540, 2023).
Zinc deficiency (5 papers, 2013 to 2026). A deficiency of the essential metal Zinc; an essential cofactor for many enzymes. "The activity of ornithine transcarbamylase, a zinc-dependent enzyme, decreases under conditions of zinc deficiency such that the body’s capacity to detoxify ammonia in the liver is lowered, worsening the condition of the liver." (PMID 32331308, 2020). "Ornithine transcarbamylase, which plays an essential role in the urea cycle, is a zinc-dependent enzyme, the activity of which decreases under conditions of zinc deficiency." (PMID 32331308, 2020). "Zinc deficiency can interfere with ornithine transcarbamylase (OTC) function, which is possible in this patient." (PMID 27144037, 2016). "Animal models have shown zinc deficiency decreases the activity of ornithine transcarbamylase, while zinc supplementation markedly increases hepatic ornithine transcarbamylase activity." (PMID 23742732, 2013). "Another possible contributory factor was the substitution of micronutrients, most notably zinc– an important co-factor of the urea cycle enzyme ornithine transcarbamylase, which may undergo reversible functional impairment during zinc deficiency." (PMID 39607664, 2024).
chronic granulomatous disease (4 papers, 2006 to 2024). Chronic granulomatous disease (CGD) is a rare primary immunodeficiency, mainly affecting phagocytes, which is characterized by an increased susceptibility to severe and recurrent bacterial and fungal infections, along with the development of granulomas. "Larger deletions in the XK gene may also involve chronic granulomatous disease, dystrophinopathy, retinitis pigmentosa and ornithine transcarbamylase deficiency (Peikert, Hermann, and Danek 2022)." (PMID 39324427, 2024).
colorectal cancer (4 papers, 2018 to 2025). A primary or metastatic malignant neoplasm that affects the colon or rectum. "Here, we show that colorectal cancers (CRCs) display negligible expression of OTC and, in subset of cases, ASS1 proteins." (PMID 30108309, 2018). "However, this hypothesis needs to be tested, since all three colorectal cancer cell lines in this study showed undetectable levels of OTC protein." (PMID 37762044, 2023). "Animal studies reveal that colorectal cancer (CRC) cells accumulate ammonium due to downregulation of transcription factors HNF4-α and ornithine transcarbamylase (OTC), a phenomenon also observed in CRC patients." (PMID 41179661, 2025). "A recent report has shown that some colorectal cancer cell lines have low ASS1 and OTC expression, which renders these cell lines arginine auxotrophic (dependant on extracellular arginine), similar to our Apc-Ass1 knockout model." (PMID 34599156, 2021).
Encephalopathy (4 papers, 2014 to 2024). Encephalopathy is a term that means brain disease, damage, or malfunction. "An R40H mutation in the OTC gene was identified in case 1; however, the hyperammonemic encephalopathy was rapidly exacerbated by corticosteroid administration, and 5 days of hemodialysis was required to normalize serum ammonia levels." (PMID 35346058, 2022). "In one patient, who had died at 10 years for hyperammonemic encephalopathy, the residual OTC activity was 4% in the liver." (PMID 38167094, 2024).
McLeod syndrome (4 papers, 2012 to 2024). "Given that some patients with McLeod syndrome harbor mutations in OTC and DMD, the secondary pathology may arise from mutations in genes contiguous to the primary causative gene." (PMID 39000307, 2024). "Quite recently, details have been revealed from two patients of five exhibiting contiguous gene syndrome (CGS) associated with deletions of the XK gene responsible for McLeod syndrome (OMIM 314850) and the ornithine transcarbamylase (OTC) gene responsible for OTC deficiency (OTCD [OMIM 311250])." (PMID 22383943, 2012).
phenylketonuria (4 papers, 2014 to 2026). Phenylketonuria (PKU) is the most common inborn error of amino acid metabolism and is characterized by mild to severe mental disability in untreated patients. "Conditions like glycogen storage diseases, ornithine transcarbamylase (OTC) deficiency, and phenylketonuria (PKU) are among those being explored in ongoing trials." (PMID 41573373, 2026).
carnitine deficiency (3 papers, 2012 to 2021). "Neonatal intrahepatic cholestasis caused by citrin deficiency, ornithine transcarbamylase deficiency and primary carnitine deficiency were confirmed by DNA analysis." (PMID 22364411, 2012).
Cirrhosis (3 papers, 2020 to 2025). A chronic disorder of the liver in which liver tissue becomes scarred and is partially replaced by regenerative nodules and fibrotic tissue resulting in loss of liver function. "The oral zinc supplementation has proved to be effective in reducing blood ammonia and increasing liver ornithine transcarbamylase activity in carbon tetrachloride-induced cirrhosis." (PMID 32190227, 2020).
fibrosis (3 papers, 2021 to 2025). the formation of excess fibrous connective tissue in an organ or tissue in a reparative or reactive process. "A significant downregulation in mRNA was observed in CPS1 and ornithine transcarbamylase (OTC1) in simple steatosis and NASH-fibrosis patients versus controls." (PMID 35232986, 2022). "We found the expression of OTC, CPS1, ASS1, and ASL was highly upregulated in BLM-induced fibrosis, and these enzymes were also downregulated after treatment with TL." (PMID 33995084, 2021). "Additionally, there was a downregulation in OTC-1 in bland steatosis (0.28 fold [CI95% 0.08–0.48]) vs. healthy controls (onefold [CI95% 0.84–1.18]) (p < 0.0001), as well as in NASH-fibrosis patients when also compared to healthy individuals (0.50 fold [CI95% 0.06–0.94]) (p = 0.01)." (PMID 35232986, 2022).
hemophilia B (3 papers, 2006 to 2020). Hemophilia B is a form of hemophilia characterized by spontaneous or prolonged hemorrhages due to factor IX deficiency. "Preclinical models of such disorders include hemophilia B, hereditary tyrosinemia type I, and ornithine transcarbamylase deficiency." (PMID 28238287, 2017).
liver cancer (3 papers, 2022 to 2023). An epithelial or non-epithelial malignant neoplasm that arises from the liver. "The low expression of OTC was related to larger tumor size and advanced stage, as well as shorter survival in liver cancer." (PMID 37387559, 2023).
liver fibrosis (3 papers, 2021 to 2024). "The newly generated OTC knock‐out mouse model that develops liver fibrosis and chronic liver damage might be a suitable model to investigate this issue in long‐term studies." (PMID 33369168, 2021). "Moreover, increased liver fibrosis has been observed in heterologous OTC-KO mice." (PMID 35327967, 2022).
maple syrup urine disease (3 papers, 2019 to 2022). An autosomal recessive inherited disorder caused by mutations in the BCKDHA, BCKDHB, DBT, and DLD genes. "The samples were derived from cirrhotic (e.g., biliary atresia, PFIC II, autoimmune hepatitis) and non-cirrhotic (e.g., Maple syrup urine disease, ornithine transcarbamylase deficiency) livers." (PMID 36497057, 2022).
Sepsis (3 papers, 2015 to 2023). Sepsis is defined as life-threatening organ dysfunction caused by a dysregulated host response to infection. "However, the metabolic response to sepsis appears strikingly similar to urea cycle disorders, in particular ornithine transcarbamylase deficiency." (PMID 37410734, 2023). "As a compensation, ornithine transcarbamylase (OTC) may help to restore the citrulline availability during conditions with low protein intake, such as sepsis and endotoxemia." (PMID 25699985, 2015).
X-linked disease (3 papers, 2017 to 2021). X-linked form of disease. "In one false positive case (male NB-10) involving X-linked disease OTC, the test found two DNA variants in the OTC gene consistent with the original MS MS positive result." (PMID 30612563, 2019). "Ornithine transcarbamylase (OTC) deficiency is an infrequent X-linked inherited disorder described by partial or complete absence of the enzyme OTC." (PMID 34977000, 2021).
acute liver failure (2 papers, 2022 to 2026). Rapid deterioration of liver function causing encephalopathy and coagulopathy. "The administration of ornithine activates two essential enzymes in the urea cycle, carbamoylphosphate synthetase (CPS) and ornithine transcarbamylase (OTC), that trigger the removal of highly toxic ammonia, which is usually associated with acute liver failure." (PMID 35453442, 2022).
brain tumors (2 papers, 2017 to 2021). "A recent study reported decreased OTC expression in HCC patients’ samples; OTC is one of the characteristic arginine metabolism genes in pediatric sarcomas, brain tumors, and acute lymphoblastic leukemia." (PMID 33915902, 2021). "Here we show in large in silico patient cohorts that paediatric sarcomas and brain tumours express predominately the arginine transporter SLC7A1 and the arginine metabolising enzyme Arginase 2 (ARG2), but have low-absent expression of OTC." (PMID 28969007, 2017).
citrin deficiency (2 papers, 2012 to 2025). "Enzyme defects include deficiency of carbamylphosphate synthase, N-acetylglutamate synthase, ornithine transcarbamylase, argininosuccinate lyase and arginase, transporter defects are citrin deficiency and HHH-syndrome." (PMID 40285952, 2025).
Fabry disease (2 papers, 2025). Fabry disease (FD) is a progressive, inherited, multisystemic lysosomal storage disease characterized by specific neurological, cutaneous, renal, cardiovascular, cochleo-vestibular and cerebrovascular manifestations. "For instance, AAV (adeno-associated virus)-mediated gene therapy has shown promise in conditions such as ornithine transcarbamylase (OTC) deficiency, Fabry disease, and spinal muscular atrophy." (PMID 41404425, 2025).
glioma (2 papers, 2017 to 2024). A benign or malignant brain and spinal cord tumor that arises from glial cells (astrocytes, oligodendrocytes, ependymal cells). "In all tumour types studied, except glioma, ARG2 and OTC ranked gene lists significantly correlated with KRAS signaling." (PMID 28969007, 2017).